SLC67A2 (solute carrier family 67 member 2)
Synonyms: MFSD9; MGC11332
Tractability: Antibody: UniProt predicts a signal peptide or a membrane-spanning region. PROTAC: ubiquitination databases record sites on it; its protein half-life has been measured.
Gene: Protein-coding gene on chromosome 2 (102,714,630 to 102,736,888, reverse strand). Ensembl gene ENSG00000135953.
Subcellular location: Membrane
Subcellular location (Human Protein Atlas): Nucleoli; Nucleoli rim
Gene Ontology:
Molecular function: transmembrane transporter activity
Biological process: transmembrane transport
Cellular component: membrane
Genetic constraint (gnomAD): Loss-of-function variants: 19 observed, 19.22 expected, observed/expected ratio (o/e) 0.99, 90% interval 0.69 to 1.45. The upper end of that interval is the gene's LOEUF score, 1.45, which puts it in group 5 of 6, group 1 being the genes least tolerant of losing a copy. Missense variants: 626 observed, 618.85 expected, observed/expected ratio (o/e) 1.01, 90% interval 0.95 to 1.08. Synonymous variants: 294 observed, 266.31 expected, observed/expected ratio (o/e) 1.1, 90% interval 1 to 1.22.
Homologues: Orthologues: chimpanzee MFSD9 (97% identical), macaque MFSD9 (93% identical), rabbit MFSD9 (75% identical), mouse Mfsd9 (72% identical), dog MFSD9 (72% identical), rat Mfsd9 (70% identical), pig MFSD9 (68% identical), guinea pig MFSD9 (66% identical), zebrafish mfsd9 (54% identical), tropical clawed frog mfsd9 (51% identical), Caenorhabditis elegans F27D9.2 (13% identical), Caenorhabditis elegans mfsd-8 (12% identical), and 6 more. Paralogues in human: SLC75A1 (20% identical), SLC71A1 (19% identical), SLC71A2 (18% identical), MFSD8 (14% identical), MFSD1 (13% identical), SLC61A1 (13% identical).